TNF (tumor necrosis factor)
Diseases named in the same sentence as TNF in open-access papers (continued):
Sharing a sentence is not in itself a finding about the gene and the disease.
myeloma (continued). "A subset of multiple myeloma cell lines and also about half of the primary MM samples were found to be sensitized for TNF-induced cell death by MLN4924." (PMID 31406107, 2019). "This suggests that the variable levels of cell surface expression of TNFR1 in myeloma cell lines are decisive for TNF/MLN4924 sensitivity." (PMID 31406107, 2019). "MM cells were found to be generally TNF resistant but MLN4924 sensitized a subset of myeloma cells for TNFR1-induced cell death." (PMID 31406107, 2019). "To figure out the molecular basis of TNF/MLN4924 resistance of myeloma cells, we initially evaluated the sensitivity of the TNF-resistant MM cell lines KMS-11, AMO-1, and L-363 for TRAIL-induced and CD95L-induced cell death." (PMID 31406107, 2019). "Since TNF has been identified as a factor which is expressed in MM43–45, we evaluated in this study the different multiple myeloma cell lines and primary myeloma cell samples with respect to their TNF sensitivity in the presence of MLN4924." (PMID 31406107, 2019). "A striking observation was that only a subset of the myeloma cell lines and about half of the primary MM samples were killed by TNF/MLN4924." (PMID 31406107, 2019). "It has been also suggested that TNF, which has a very short serum half-life, promotes survival of myeloma cells within the tumor microenvironment." (PMID 31134075, 2019). "Multiple myeloma cells have been shown to produce factors that inhibit osteoblast differentiation and growth, including IL-3, TNF-alpha, and TGF-beta." (PMID 29867053, 2018). "TNF not only supports the pro-inflammatory tumor microenvironment but also induces the expression of important NF-κB-target pro-survival factors in myeloma cells." (PMID 29772694, 2018). "TNF-α is one of the major pro-inflammatory cytokines secreted from myeloma cells and can stimulate bone marrow stromal cells to release IL-6, which can act as a potential growth factor for myeloma cells." (PMID 29773987, 2018). "The authors established three mouse myeloma cell lines engineered to secrete tumor necrosis factor-α (TNF-α), IL-2, and Interferon-γ (IFN-γ)." (PMID 29534557, 2018). "This evidence suggests that multiple myeloma cells exploit the collaboration of Notch and TNFα signaling pathways to induce bone resorption in multiple myeloma and possibly RANKL-mediated immunosuppression." (PMID 30154786, 2018). "Thalidomide, an inhibitor of E3 ubiquitin ligases, increased the degradation of TNFα mRNA and reduced the production of TNFα, making thalidomide a good candidate for the treatment of multiple myeloma." (PMID 30069488, 2018). "Pro-inflammatory cytokine TNF activates canonical NF-κB signaling in both BMSCs as well as myeloma cells, and is also produced by the canonical pathway." (PMID 29772694, 2018). "Qiu and colleagues subsequently showed that clarithromycin reduced interleukin-6 (IL-6) and tumor necrosis factor (TNF) activity in myeloma cell lines." (PMID 29743095, 2018). "BCL6 expression can be stimulated by cytokines such as IFN-γ, IL-6, type I IFN, IL-12, and TNF-α in myeloma or TFH cells." (PMID 30687256, 2018). "The cytokines IL-6 and TNF-α have been reported to be involved in the progression myeloma and hence the effect of CSL and bortezomib on the levels of these two cytokines in serum samples obtained from mice was analyzed using an ELISA kit." (PMID 29773987, 2018). "Remarkably, NF-κB dependent RelB synthesis perpetuated a sustained RelB:p50 activity upon TNF stimulation of these myeloma cells." (PMID 29772694, 2018). "Rather autoregulatory RelB control mediated precarious collaboration between widespread cell-intrinsic mutations in the non-canonical NFκB module and dynamical signaling induced by TNF in multiple myeloma." (PMID 27641334, 2017). "Genetic analyses and mathematical modeling studies substantiated that depletion of p100 in myeloma cells triggers this autoregulatory loop to promote perpetuating RelB:p50/NFκB response to TNF." (PMID 27641334, 2017).
myeloma (continued). "Taken together, p100 depletion reinforced pro-survival TNF response in multiple myeloma by prolonging classical NFκB function via the autoregulatory RelB pathway." (PMID 27641334, 2017). "Following treatment with BI836909, selective lysis of BCMA-positive myeloma cells, activation and proliferation of T cells, as well as release of multiple key cytokines related to effector T cell function (IFNγ, IL-2, IL-6, TNFα, IL-10) were noted." (PMID 31548533, 2017). "The IκB kinase inhibitor PS-1145 was shown to block TNF-α-induced NF-κB activation in multiple myeloma cells through inhibition of IκBα phosphorylation and degradation." (PMID 27147748, 2016). "Multiple myeloma MSCs have induced expression of high levels of arginase-1, TNF-α, and angiogenic factor PROK2 in MDSCs, thus contributing to tumor development." (PMID 27630452, 2016). "The role of TNF-α and IL-6 in the progression of myeloma cell growth, survival, angiogenesis, and osteoclastogenesis and the inhibition of osteoblast activity is well established, as well as their adverse prognostic significance in this hematological neoplasm." (PMID 26925413, 2016). "Despite this notorious effect, intensive research has been carried out with thalidomide due to its efficacy of inhibiting tumor necrosis factor (TNF)-α secretion and treating multiple myeloma and other hematologic malignancies." (PMID 27478739, 2016). "Stimulation of the monocytes enriched from the bone marrow of myeloma patients with the TLR8 ligand CL075 induced TNF α production." (PMID 26029369, 2015). "Enhanced IL-2 secretion by CD3+/CD56+ cells and production of TNF-α led to enhanced killing of myeloma cells." (PMID 25287778, 2015). "Bone marrow stroma offered no protection for 5TGM1-ΔF cells in cocultures treated with tumor necrosis factor (TNF), indicating a cell-autonomous anti-myeloma effect." (PMID 26009993, 2015). "Tumor necrosis factor-alpha (TNF-α) stimulated IL-6 production is also suppressed by inhibition of JAK2 in multiple myeloma cells." (PMID 26491227, 2015). "Human and murine myeloma cells, including 5TGM1 cells, secrete both TNF-α and TNF-β, which can act as autocrine growth and survival factors." (PMID 26009993, 2015). "Elevated serum levels of TNFSF13 have been reported in oral cavity cancers, and are correlated with increased serum TNF levels, angiogenesis and poor prognosis in multiple myeloma." (PMID 25120605, 2014). "Previous study reported that co-treatment with TNF-α-neutralizing antibody and melphalan induced enhanced expression of Bim in multiple myeloma cell lines." (PMID 24465927, 2014). "Some cytokines such as IL-7, IL-3, IL-6, TNF-α produced by myeloma cells can inhibit the differentiation and activativity of osteoblasts and induce osteoblasts apoptosis." (PMID 25788856, 2014). "We found that the levels of TNFα and IL-6 were elevated in bone marrow aspirates of multiple myeloma patients." (PMID 24151609, 2013). "We found that some of myeloma cells including U266 cells showed stronger response to exogenous IL-6 (data not shown), and these cells also secreted more IL-6 in response to TNFα in vitro." (PMID 24151609, 2013). "IL-6 and TNFα were significantly increased in the bone marrow aspirate samples of patients with active multiple myeloma (MM) compared to those of normal controls." (PMID 24151609, 2013). "We also analyzed the patterns of correlation between TNFα and IL-6 and the mechanisms of TNFα-induced IL-6 secretion from multiple myeloma cells." (PMID 24151609, 2013). "As a naturally occurrence, cytokine of inflammatory and immune responses, TNF-α has been involved in the pathogenesis of hematologic malignancies, such as multiple myeloma, myelodysplastic syndrome (MDS), and acute myelogenous leukemia (AML)." (PMID 24040369, 2013). "In this study, we investigated the biological mechanism of action of the TNFα in human myeloma cells." (PMID 24151609, 2013).
myeloma (continued). "Numerous studies revealed that TNFα induces IL-6 secretion from multiple myeloma cells and bone marrow stromal cells through NF-κB pathway." (PMID 24151609, 2013). "TNFα potently stimulates IL-6 secretion by stromal cells and osteoblasts, and accumulated IL-6 stimulates growth of multiple myeloma cells." (PMID 24151609, 2013). "Taken together, we analyzed the correlation of high levels of TNFα with several prognostic factors in multiple myeloma patients and the signaling regulation in vitro." (PMID 24151609, 2013). "In the aspirates of patients with multiple myeloma, elevated TNFα level has been observed in numerous studies and this is correlated with poor prognosis." (PMID 24151609, 2013). "The major mechanism by which TNFα mediates progression of multiple myeloma cells is via regulation of nuclear factor kappa B (NF-κB) transcription factor." (PMID 24151609, 2013). "In multiple myeloma, BMSCs up-regulate the secretion of several factors (IL-6, IGF-1, VEGF, FGF, SDF-1 and TNFα) as a result of their direct interaction with myeloma cells through integrins and soluble factors produced by myeloma cells." (PMID 24304929, 2013). "TNFα and IL-6, as pivotal factors for myeloma, can be ideal targets for therapeutic purpose, either directly or by inhibiting interaction with BMSCs." (PMID 24151609, 2013). "Nuclear factor κB (NFκB) activation plays a crucial role in anti-apoptotic responses in response to the apoptotic signaling during tumor necrosis factor (TNFα) stimulation in Multiple Myeloma (MM)." (PMID 21408099, 2011). "Other examples of formerly validated genes are Baff and April, 2 members of the TNF superfamilly that were already shown to be highly expressed by the myeloma microenvironment compared to the MMC themselves by real-time RT-PCR." (PMID 20465808, 2010). "The inhibitory action of pristimerin against NF-κB has been documented in murine macrophages (RAW 264.7) induced by lipopolysaccharide and in human myeloma cells induced by TNFα." (PMID 20482842, 2010). "IL-1, VEGF, macrophage inhibitory factor (MIP) 1α, TNF-α, receptor activator of nuclear factor-κB (RANK) ligand and osteoprotegerin are agents mediating the osteoclastic activity that brings about the myeloma-associated osteolytic bony lesions." (PMID 19152712, 2009). "The starting point of this study was our observation that IL-6, IL-21 and TNF-α induced expression of BCL3 in the myeloma cell lines OH-2 and IH-1." (PMID 19191868, 2009). "The large amount of osteoclastogenic TNFα in multiple myeloma may be conferred a constant expression of SELENOW during RANKL-induced osteoclast differentiation." (PMID 38683225, 2024). "Furthermore, elotuzumab has been shown to enhance NK cell activation and myeloma cell killing through interleukin-2 (IL-2) and tumor necrosis factor alpha (TNF-α) pathways." (PMID 38966176, 2024). "Also, the level of tumor necrosis factor alpha (TNFα), a pathological osteoclastogenic factor, is increased in the PBMCs and serum of patients with multiple myeloma." (PMID 38683225, 2024). "Thus, the increased killing of the myeloma cell lines in the presence of higher concentration of LCL161 (5 μM) is likely due to something other than sensitization of TNFα-mediated killing." (PMID 37138866, 2023). "Furthermore, higher ferritin levels inhibit tumor necrosis factor-induced apoptosis; thus, supporting myeloma cell survival." (PMID 37240197, 2023). "IgA could activate the immune function by modulating the production of key cytokines such as TNF, IL-6, and IL-2 by human myeloma cells." (PMID 37050214, 2023). "Moreover, release of IL-6 and TNF-α by TAMs increases the vascular leakiness of newly formed tumor vessels in Vk*MYC myeloma mice thus facilitating the entrance of single plasma cell clones into the blood circulation." (PMID 37744361, 2023). "This work demonstrated that myeloma cells down-regulate adiponectin in BMAds via TNF-α." (PMID 36909335, 2023).
myeloma (continued). "However, further studies revealed that the drug inhibited tumor necrosis factor-alpha signaling, and it was subsequently approved for the treatment of erythema nodosum leprosum, a life-threatening complication of leprosy, and then multiple myeloma." (PMID 35906687, 2022). "IL-1b, TNF-a, IL-6, and IL-10 may contribute to osteopenia; IL-6 and IL-10 may be responsible for gammopathies and multiple myeloma; IL-1b, TNF-a, and IL-6 may have a role in the activation of hypermetabolism." (PMID 36498496, 2022). "Besides, macrophages exposed to these heparinase-containing exosomes enhance their ability to secrete tumor necrosis factor-α (TNF-α), an important growth factor that promotes survival of myeloma cells." (PMID 35692747, 2022). "It had reported that IL-6 production could be induced by TNF-α in a dose-dependent manner in myeloma cells." (PMID 35342422, 2022). "Alternatively, the accumulation of CD69+ TTE within MILs may contribute to local inflammation through the production of the pro-inflammatory cytokines IFN-γ and TNF-α and promote myeloma growth." (PMID 33708212, 2021). "Thalidomide, targeting tumor necrosis factor-α (TNF-α), for multiple myeloma." (PMID 34956857, 2021). "We conclude that, coupled with our prior work showing that ex vivo virotherapy with unarmed MYXV can be an effective therapeutic strategy against multiple myeloma in the BM and spleen, this systemic delivery strategy with TNF-armed MYXV can effectively treat metastatic disease in the lung." (PMID 34553039, 2021). "Thalidomide is a potent immunomodulator and a TNF-α inhibitor, originally used for treatment of multiple myeloma and erythema nodosum leprosum and evaluated for repurposing across numerous neurological disorders due to its multipotent pleiotropic characteristics." (PMID 33343293, 2020). "The ability of myeloma cells to downregulate adiponectin was dependent at least in part on TNF‐α." (PMID 31886918, 2020). "All multiple myeloma cell lines investigated were resistant against treatment with TNF alone." (PMID 31406107, 2019). "Since TNF is typically expressed by immune cells present in the tumor microenvironment of myeloma cells and other cancer entities, we explored the possibility of a synergistic cytotoxic effect of soluble recombinant TNF and MLN4924 on a panel of 10 myeloma cell lines." (PMID 31406107, 2019). "Our current study indicated that p100 depletion might enable RelB-dependent, late-acting expressions of pro-survival genes in myeloma cells subjected to brief TNF stimulation." (PMID 31134075, 2019). "Furthermore, chronic TNF treatment of these p100-depleted myeloma cells induced RelA:p50 as well as RelB:p50 complexes, both of which activated the expression of pro-survival factors." (PMID 31134075, 2019). "Relative survival of TNF-treated myeloma cells was between 86% and 105%." (PMID 31406107, 2019). "After isolation, the primary myeloma cells were stimulated with TNF and/or MLN4924." (PMID 31406107, 2019). "Finally, one elegant study showed a complementary effect of Notch and TNFα in multiple myeloma-induced bone disease." (PMID 30154786, 2018). "Indeed, disruption of the TNF autocrine loop was shown to sensitize myeloma cells to apoptosis-inducing anticancer drugs ex vivo." (PMID 29772694, 2018). "Interestingly, the pharmacological blockers of TNF-α; namely thalidomide and its derivatives and bortezomib, have been reported to exhibit significant anti-myeloma activity." (PMID 29773987, 2018). "In addition TNF-α production contributed significantly to NK cell activation and myeloma cell cytotoxicity." (PMID 30455698, 2018). "Here we report that myeloma-associated non-canonical aberrations reinforce pro-survival TNF signaling in producing a protracted TRAIL-refractory state." (PMID 27641334, 2017).
myeloma (continued). "Tumor-promoting cytokines, such as tumor necrosis factor (TNF), induce nuclear factor-κB (NFκB)- driven expression of pro-survival factors, which confer resistance in myeloma cells to apoptotic insults from TNF-related apoptosis-inducing ligand (TRAIL) and other chemotherapeutic drugs." (PMID 27641334, 2017). "Here, we demonstrate that non-canonical NFκB mutations collaborate with TNF signaling in producing a protracted TRAIL-refractory state in myeloma cells." (PMID 27641334, 2017). "More so, autoregulatory RelB synthesis prolonged this TNF-induced RelB:p50 activity in myeloma cells harboring non-canonical mutations." (PMID 27641334, 2017). "Intriguingly, pro-survival TNF response is attributed to RelB:p50, and not RelA:p50, NFκB activity in myeloma cells harboring non-canonical mutations." (PMID 27641334, 2017). "Interaction of myeloma cells with bone marrow stromal cells (BMSCs) via some key factors (SDF-1, TGFβ, IFNγ, IL6, and TNFα, etc.), induces pleiotropic anti-apoptotic mechanisms, thereby rendering multiple myeloma cells resistant to established therapeutic regimens." (PMID 28032590, 2017). "Furthermore, these results extended the possibility that TNF-induced RelB:p50 activity provides for the pro-survival NFκB transcription function in p100-depleted myeloma cells." (PMID 27641334, 2017). "We hypothesized that, in myeloma patients, proinflammatory cytokine tumor necrosis factor-alpha (TNF-α) upregulates the production of interleukin-6 (IL-6), which then mediates increased secretion of MCP-1." (PMID 26925413, 2016). "Cytotoxicity assays were performed by incubating myeloma cells with TNF-α and IFN-γ." (PMID 25287778, 2015). "Similarly, cIAPs also play an important role in NF-κB-mediated protection from TNF-α-induced apoptosis in myeloma cells." (PMID 26009993, 2015). "Interestingly, TNF-α blockers such as thalidomide and other immunomodulatory agents have exhibited significant anti-myeloma activity." (PMID 24504138, 2014). "In addition to TNFα, IL-6, produced from multiple myeloma cells as well as bone marrow stromal cells, is also a major growth factor for tumor cells regulating various biological signaling." (PMID 24151609, 2013). "In conclusion, blockage of JAK/STAT-mediated NF-κB activation was highly effective in controlling the growth of MM cells and, consequently, an inhibitor of TNFα-mediated IL-6 secretion would be a potential new therapeutic agent for patients with multiple myeloma." (PMID 24151609, 2013). "Bone destruction is generated in multiple myeloma patients which is unique from other hematologic malignancies; this phenomenon might be related to increase TNFα levels." (PMID 24151609, 2013). "Patients of POEMS have higher levels of IL-1B, TNF-alpha and IL-6 as compared to multiple myeloma." (PMID 24349810, 2013). "Therefore, NF-κB activation in BMSCs enhances positive loop with adherent multiple myeloma cells by secretion of growth factors such as IL-6, TNFα, and HGF." (PMID 24151609, 2013). "So, we hypothesized that TNFα is one of the major factors that regulate IL-6 secretion from multiple myeloma cells." (PMID 24151609, 2013). "TNFα is one of the factors elevated in multiple myeloma patients." (PMID 24151609, 2013). "Both IL-6 and TNF-α have a proliferative effect on myeloma cells." (PMID 19191868, 2009). "Microarray experiments done in our laboratory showed that the myeloma cell growth factors interleukin (IL)-6, IL-21 and tumor necrosis factor (TNF)-α all induced expression of the putative oncogene BCL3 in the myeloma cell lines IH-1 and OH-2 (paper in preparation)." (PMID 19191868, 2009). "Angiogenesis, downregulation of tumor necrosis factor, interference with stromal cell/myeloma adhesive properties and stimulation of natural killer cells are thought to be the mechanisms by which it exerts its beneficial effects in multiple myeloma." (PMID 18778468, 2008).